VSIG4 (V-set and immunoglobulin domain containing 4)
Diseases named in the same sentence as VSIG4 in open-access papers (continued):
Sharing a sentence is not in itself a finding about the gene and the disease.
Stroke (1 paper, 2023). Sudden impairment of blood flow to a part of the brain due to occlusion or rupture of an artery to the brain. "Our findings showed that C1QC, VSIG4, and CFD can potentially serve as diagnostic blood biomarkers of AF-CE; novel nomogram and the companion website can help clinicians to identify high-risk individuals, thus helping to guide treatment decisions for stroke patients." (PMID 36644582, 2023).
Ureteral obstruction (1 paper, 2023). Obstruction of the flow of urine through the ureter. "An inflammatory response was aggravated in a VSIG4 knock-out unilateral ureteral obstruction (UUO) model." (PMID 36836636, 2023). "Here, we investigated VSIG4 expression in unilateral ureteral obstruction (UUO), doxorubicin-induced kidney injury mouse, and doxorubicin-induced podocyte injury models." (PMID 36836636, 2023).
Vestibular schwannoma (1 paper, 2022). A vestibular schwannoma (also known as acoustic neuroma, acoustic neurinoma, or acoustic neurilemoma) is a benign, usually slow-growing tumor that develops from the VIIIth cranial nerve supplying the inner ear. "Combined with the analysis of data in the GEO database and immunohistochemical verification, it was concluded that HLA-DPB1 and VSIG4 may be candidate biomarkers and potential therapeutic targets for patients with sporadic vestibular schwannoma." (PMID 36304995, 2022).
viral fulminant hepatitis (1 paper, 2017). "We further investigated the potential role of Vsig4 in viral fulminant hepatitis caused by MHV-3 infection, in which the virus-induced exaggerated inflammation causes severe pathogenesis largely due to the M1 macrophage-dependent “cytokine storm”7." (PMID 29109438, 2017). "Forced expression of Vsig4 in mice ameliorates MHV-3-induced viral fulminant hepatitis." (PMID 29109438, 2017). "Interestingly, forced overexpression of Vsig4 ameliorates MHV-3-induced viral fulminant hepatitis." (PMID 29109438, 2017).
tumor (62 papers, 2017 to 2026). "Targeting VSIG4 not only disrupts FAO‐dependent M2 polarization but also synergistically enhances tumour susceptibility to PD‐1 blockade." (PMID 40405491, 2025). "V-set and immunoglobulin domain-containing 4 (VSIG4) positive tumor-associated macrophage (VSIG4+ TAM) is an immunosuppressive subpopulation newly identified in aggressive cancers." (PMID 39920772, 2025). "VSIG4-expressing tumor-associated macrophages (TAMs) can inhibit tumor-specific CD8+ T cell proliferation and cytokines production, which function as a suppressor of anti-tumor immune response." (PMID 38846981, 2024). "Due to the pan-cancer expression of VSIG4 on tumor-associated macrophages, tumor tissue from all solid tumor types was accepted as it became available over the duration of the study." (PMID 38892347, 2024). "Bioinformatics study showed positive correlation between VSIG4 and infiltration of neutrophil and tumor-associated macrophages (TAMs) in PDAC, and it inhibited the secretion of cytokines." (PMID 37097516, 2023). "On the other hand, we noticed that there is a significant recruitment of myeloid cells including neutrophil and tumor-associated macrophages (TAMs) in high VSIG4 tissues and it inhibited the secretion of cytokines according to bioinformatics study." (PMID 37097516, 2023). "It has been found that in tumor microenvironment, VSIG4 is expressed on M2 macrophages or tumor-associated macrophages (TAM)." (PMID 36304995, 2022). "Then, various tumor infiltration deconvolution methods were applied; we found that VSIG4 was one of the most commonly associated M2 macrophage biomarkers." (PMID 33692827, 2021). "Notably, cell-cell interaction analysis revealed that SPP1 signaling between TAMs and tumor cells and/or neutrophils dramatically decreased in TAMs from VSIG4-deficiency mice." (PMID 39920772, 2025). "Therefore, identifying the mechanism underlying the anti-tumor immunity of VSIG4 inhibition would enhance the comprehension of VSIG4-based immunotherapy." (PMID 39920772, 2025). "VSIG4 expression is specific for tumor-associated and select tissue-resident macrophages." (PMID 38892347, 2024). "We also confirmed that the depletion of NK cells reduced the anti-tumor effect of VSIG4-KO to a certain extent and that the double depletion of CD8+ T and NK cells showed a slight synergistic effect." (PMID 39920772, 2025). "The proportions of neutrophils, monocytes, and mast cells in the transplanted tumor tissues of VSIG4-KO mice were profoundly reduced compared to those of wild-type mice." (PMID 39920772, 2025). "In summary, targeting VSIG4+ TAMs effectively enhanced anti-tumor immunity by increasing the number of cytotoxic lymphocytes." (PMID 39920772, 2025). "In view of the key regulatory properties of VSIG4+ TAMs in tumor immunity, the specific mechanism by which VSIG4+ TAMs promote tumor immune escape was explored by single-cell transcriptome analysis of mATC-derived tumors." (PMID 39920772, 2025). "VSIG4, a transmembrane protein specifically expressed on tissue-resident macrophages, plays a key regulatory role in tumor immunology." (PMID 41150752, 2025). "Overall, these results indicated that the anti-tumor immunity induced by VSIG4 inhibition was primarily depended on CD8+ T cells." (PMID 39920772, 2025). "Analysis of clinical tumor samples indicated that high expression of VSIG4 correlated with low CD8+ T cell infiltration and high Foxp3+/CD8+ T cell ratio." (PMID 39920772, 2025). "To evaluate the role of VSIG4+ TAMs in tumor growth and progression, we selected highly aggressive PDAC and ATC as main research subjects." (PMID 39920772, 2025). "Collectively, our study identifies the clinical value of VSIG4 blockade in reshaping the immune microenvironment of immunosuppressive tumours and provides a novel perspective for understanding the role of TAMs in modulating anti‐tumour immunity." (PMID 40405491, 2025).
tumor (continued). "Subcutaneous xenograft models evaluated the tumour growth inhibition efficacy of VSIG4 blockade as monotherapy and combined with immune checkpoint inhibitors (ICIs)." (PMID 40405491, 2025). "Given that patients with ATC have a median overall survival of only 4.8 months, the profound anti-tumor effect of VSIG4 blockade provides a promising opportunity for immunotherapy." (PMID 39920772, 2025). "In murine experiments, targeted knockdown of VSIG4 resulted in inhibited tumour growth, accompanied by a reduction in the proportion of M2‐TAMs and exhausted T cells, alongside enhanced activity of CD8+ T cells." (PMID 40405491, 2025). "We found mice treated with anti-VSIG4 or anti-SPP1 antibody alone exhibited slower tumor growth, and combination therapy with VSIG4 and SPP1 blockade synergistically enhanced anti-tumor activity without affecting body weight." (PMID 39920772, 2025). "Within the TME, VSIG4+ TAMs demonstrate the ability to suppress tumor immunity by negatively regulating T cell activity and are considered as a promising target for tumor immunotherapy." (PMID 40539047, 2025). "VSIG4 inhibition demonstrated dual efficacy in suppressing oncogenesis and reprogramming the tumour immune microenvironment (TIME), with synergistic enhancement of PD‐1 blockade." (PMID 40405491, 2025). "It was also enriched in the biological progress of “humoral immune response”, suggesting a role for VSIG4 in tumor immunology." (PMID 40539047, 2025). "On the contrary, VSIG4 promoted macrophage M2 polarization and induced malignant progression of tumour cells by promoting M2 macrophage secretion of heparin‐bound epidermal growth factor." (PMID 40405491, 2025). "Results showed that optimized siRNA in vivo significantly reduced VSIG4 expression and tumour growth." (PMID 40405491, 2025). "In light of the critical role macrophages play as constituents of immune cells infiltrating tumours, our conjecture stands that VSIG4 triggers immunosuppression through the facilitation of macrophage polarization and recruitment." (PMID 40405491, 2025). "In this study, the anti-tumor effects by targeting VSIG4+ TAMs were investigated using VSIG4-knockout (KO) mouse models and an anti-VSIG4 antibody, especially in two extremely aggressive cancers, PDAC and ATC." (PMID 39920772, 2025). "The ratio of OVA-reactive CD8+ T cells in the spleen increased significantly in VSIG4-KO and VSIG4 antibody-treated mice compared to that in the control group, and similar results were also found in tumor tissues." (PMID 39920772, 2025). "We also verified the effects of VSIG4 blockade on tumor-infiltrating lymphocytes (TILs) in the mATC tumor model and obtained similar results." (PMID 39920772, 2025). "In vivo experiments confirmed that knockdown VSIG4 inhibited tumour growth and improved the efficacy of ICIs therapy." (PMID 40405491, 2025). "It further positions VSIG4 as a very important molecule for cancer progression given that multiple tumor types select a particular isoform." (PMID 38892347, 2024). "The strength of the VSIG4 antagonistic antibody effect in the set of primary human tumors gives hope that this is the agent that can be broadly applied across tumor types and patient populations." (PMID 38892347, 2024). "Across patient-derived tumor samples from multiple tumor types, anti-VSIG4 treatment resulted in the upregulation of cytokines associated with TAM repolarization and T cell activation and chemokines involved in immune cell recruitment." (PMID 38892347, 2024). "In vivo experiments demonstrate that systemic exposure to a VSIG4-inhibiting antibody induces repolarization in the tumor microenvironment, along with inducing strong tumor growth inhibition." (PMID 38892347, 2024). "08A09 was evaluated for efficacy in the syngeneic mouse tumor model, Sa1/N, to determine if the anti-VSIG4-mediated repolarization of macrophages would lead to tumor growth reduction." (PMID 38892347, 2024).
tumor (continued). "Among them, TAM-APOE represented the tumor-associated macrophages with high expression levels of APOE, CD163, and VSIG4." (PMID 39107908, 2024). "In vivo, anti-VSIG4 treatment inhibited tumor growth in a syngeneic mouse model either as a monotherapy or in combination with anti-PD-1 accompanied by macrophage repolarization and subsequent T cell activation." (PMID 38892347, 2024). "In all these tumor types, VSIG4 expression correlated with the expression of the inhibitory macrophage marker CD163, supporting that VSIG4 is mostly expressed on suppressive macrophage populations within the tumor microenvironment." (PMID 38892347, 2024). "Across multiple tumor types, anti-VSIG4 treatment resulted in a significant upregulation of cytokines involved in TAM repolarization and T cell activation and chemokines involved in immune cell recruitment." (PMID 38892347, 2024). "The relationship between IDO1 and marker genes of tumor-associated macrophages (TAMs; CCL5, CD68, and IL10), M1 (IRF5, NOS2, and PTGS2), and M2 (CD163, VSIG4, and MS4A4A) macrophages was analyzed." (PMID 39351094, 2024). "Consistent with result in HPA database, the expression level of VSIG4 is significantly higher in tumor tissues than that in normal pancreas." (PMID 37097516, 2023). "Among these genes, FCGR2A, FYN, ITGB2, and VSIG4 protein levels were increased in tumor tissues, while MMP9 protein level was decreased, which was consistent with their mRNA expression levels." (PMID 38022584, 2023). "In our study, we found that high VSIG4 expression negatively correlated with anti-tumor phenotype which is consistent with previous report." (PMID 37097516, 2023). "According to univariate analysis, VSIG4 expression level, tumor size, T classification, liver metastasis and vascular invasion are risk factors of patients’ survival." (PMID 37097516, 2023). "Pearson correlation analysis further showed that OPN was positively associated with M2 macrophage markers (CD163, VSIG4, MS4A4A, CX3CR1, and MRC1) and tumor-associated macrophage (TAM) markers (CCL2, CD68, and IL10)." (PMID 35669197, 2022). "Our data report a strong correlation between GPX7 expression with the M2 macrophages markers (CD163, VSIG4, MS4A4A), implying a potential role for GPX7 in the polarization of tumor-associated macrophages (TAM) in LGG169." (PMID 35440701, 2022). "Expression of LGR5 was significantly higher in tumor tissues while VSIG4 had higher expression levels in normal tissues (p < 0.05)." (PMID 36186438, 2022). "By examining VSIG4 expression in tumor tissues, it was found to be highly enriched in tumor-associated macrophages but not in tumor cells or other immune cells." (PMID 36189222, 2022). "HPA003903 is an antibody against VSIG4, which showed higher intensity in tumor tissue than in normal tissue." (PMID 33692827, 2021). "Further combination of VSIG4 with SPP1 blockade synergistically boosted anti-tumor activity." (PMID 39920772, 2025). "Here, we revealed the functions and mechanism of VSIG4+ TAMs in mediating tumor immune evasion." (PMID 39920772, 2025). "Furthermore, immunofluorescence staining revealed colocalization of VSIG4 with CD68, a recognized marker for macrophages, alongside a marked elevation of VSIG4 expression in tumour tissues." (PMID 40405491, 2025). "To further investigate whether VSIG4 regulates macrophage polarization to influence tumour growth in vivo, we administered either in vivo‐optimized siRNA targeting the VSIG4 gene (siVSIG4) or siNC to immunoactive mice that had been inoculated with MC38 cells." (PMID 40405491, 2025). "Moreover, GSEA revealed significant enrichment of PD‐1 signalling in VSIG4high tumours, emphasizing the positive correlation between VSIG4 and PD‐1 pathway." (PMID 40405491, 2025). "Moreover, the combination of VSIG4 blockade with a BRAF inhibitor synergistically enhanced anti-tumor activity in ATC-tumor bearing mice." (PMID 39920772, 2025).
tumor (continued). "In the microenvironment of some solid tumor, VSIG4+ TAMs are related to poor prognosis potentially by impairing anti-tumor T cell activity, and may serve as an immune checkpoint target." (PMID 40539047, 2025). "Moreover, the significant alleviation of tumour growth inhibition after the neutralization of CD8+ T cells with CD8+ T antibodies suggests that the protumour function of VSIG4 is partially achieved by creating inhibitory TIME." (PMID 40405491, 2025). "Notably, VSIG4 knockout enhanced the anti-tumor immunity of macrophages by increasing antigen-presentation associated ligand-receptor pairs between macrophages and CD8+ T cells." (PMID 39920772, 2025). "In the present study, we found that the deletion of VSIG4 effectively inhibited the development and metastasis of cancers, and the anti-VSIG4 antibody had potent therapeutic effects in a variety of mouse transplanted tumor models." (PMID 39920772, 2025). "Furthermore, we analyzed the effects of VSIG4+ TAMs intervention on the tumor microenvironment by flow cytometry." (PMID 39920772, 2025). "Emerging evidence links elevated VSIG4 expression to poorer clinical outcomes across multiple solid tumours (e.g., glioma, gastric, breast, lung, pancreatic), positioning this checkpoint protein as a crucial modulator of tumour progression." (PMID 40405491, 2025). "The DEGs including H2-K1, B2m, and H2-D1 in VSIG4-KO TAMs were significantly upregulated and related with anti-tumor signals containing positive regulation of the innate immune response, T cell-mediated cytotoxicity against tumor cells, and antigen-presenting and presentation via MHC I." (PMID 39920772, 2025). "In addition, the co‐culture system was used to verify the effect of tumour cells on the expression of VSIG4 in macrophages, and the effect of VSIG4 expression level on tumour cells in turn." (PMID 40405491, 2025). "Overall, our studies demonstrate the epigenetic regulation function of VSIG4 confers on TAMs an alternative pattern, beyond the checkpoint role of VSIG4, to shape the immunosuppressive tumor microenvironment and impair antigen-specific immunity against aggressive cancers." (PMID 39920772, 2025). "However, little is known about the impact of VSIG4+ TAMs on the tumor immune microenvironment in vivo." (PMID 39920772, 2025). "In vivo, inhibition of VSIG4 also reduced the proportion of M2 TAMs and inhibited tumour growth." (PMID 40405491, 2025). "However, the influence of VSIG4 inhibition on the TAM phenotype in the tumor microenvironment is poorly understood." (PMID 39920772, 2025). "Additionally, using the GEPIA 2021 online tool, we found a significant upregulation of VSIG4 gene expression in M2 macrophages across various tumour types, including CRC." (PMID 40405491, 2025). "Additionally, to explore CD8+ T cell‐dependent mechanisms in VSIG4 inhibition‐mediated tumour control, in vivo CD8+ T cell depletion was achieved through antibody administration." (PMID 40405491, 2025). "VSIG4-positive macrophages in the tumor microenvironment may promote cancer progression and correlate with low CD8+ T-cell frequency, high Foxp3+/CD8+ infiltrating T-cell ratios, and poor prognosis." (PMID 41376629, 2025). "In this study, we present data showing that inhibiting VSIG4 by a monoclonal antibody or by siRNA relieves VSIG4-mediated macrophage suppression and leads to repolarizing TAMs to an inflammatory phenotype capable of coordinating an anti-tumor immune response in preclinical settings." (PMID 38892347, 2024). "In this dataset, we consistently found VSIG4 expression in a diverse array of human tumor types." (PMID 38892347, 2024). "Thus, considering the counterintuitive association of IL2RA+ VSIG4 + ATAMs infiltration with favorable prognosis, if immunosuppressive molecules could be specifically targeted in this population, it could skew their phenotype to an M1, further helping eliminate the tumor." (PMID 38022609, 2023).